MYO1C (myosin IC)
Diseases named in the same sentence as MYO1C in open-access papers (continued):
Sharing a sentence is not in itself a finding about the gene and the disease.
tumor (13 papers, 2014 to 2023). "We also found significant (P = 0.0303) association comparing sample type (tumor vs hyperplasia) and MYO1C protein level, indicating that the level of MYO1C protein is significantly lower in tumors compared to hyperplasia samples." (PMID 27716847, 2016). "In deletion mapping, combined with gene expression, sequencing and epigenetic silencing, the candidate region was delimited and Myo1c was identified as one of the most likely candidates for the proposed tumor suppressor activity." (PMID 27716847, 2016). "Taken together, in the present work we provided additional evidence for potential contribution of tumor suppressor candidate MYO1C to mechanism/s involved in cell adhesion, spreading and migration, confirming and extending the earlier findings." (PMID 27716847, 2016). "Taken together the present study gives further evidence for tumor suppressor activity of MYO1C and suggests MYO1C mediates its tumor suppressor function through inhibition of PI3K pathway and its involvement in loss of contact inhibition." (PMID 27716847, 2016). "The gene adjacent to Inpp5k, and the second candidate tumor suppressor gene identified in the present work, is the molecular motor myosin 1c (Myo1c)." (PMID 26170120, 2015). "The result for Myo1c showed a good correlation between the qPCR results and protein expression level in the tumor samples, indicating that Myo1c protein was in fact down regulated in the majority of EC tumors tested compared to the control samples." (PMID 26170120, 2015). "According to Knudson’s theory of inactivation of tumor suppressor genes, if Hic1, Inpp5k and Myo1c are to behave as classical tumor suppressor genes, it is expected that both alleles of the genes be inactivated in the tumor material." (PMID 26170120, 2015). "Statistical analysis of qPCR results combined with subsequent gene mutation screening along with epigenetic and protein expression analyses suggested Inpp5k and Myo1c as the most prominent target tumor suppressor candidates in this region." (PMID 26170120, 2015). "Restoration of gene expression was detected for Myo1c and Inpp5k genes in the tumor samples at RNA and/or protein levels." (PMID 26170120, 2015). "Several studies have even proposed that products of the Myo1C gene, including NM1, may be possible tumor suppressors as the gene itself is often mutated in various types of cancers." (PMID 37816864, 2023). "Notably, the expression patterns of ANKHD1 and MYO1C transcripts differ between the cell lines, indicating that they are indeed specific for different stages of tumour progression." (PMID 31443305, 2019). "Moreover, other members of gene families that INPP5K and MYO1C belong to are suggested to function as tumor suppressor genes in a variety of cancer types." (PMID 26170120, 2015). "Myosin-1C (MYO1C), another important gene in the PI3K/AKT signalling pathway, is known to bind with PIP2 and potentially acts as a tumour suppressor." (PMID 29755656, 2018).
tumor (continued). "Results from the present work provide evidence for inhibitory function of MYO1C on cell proliferation, presumably through repression of PI3K/AKT signaling, hence supporting the initial hypothesis of tumor suppressor activity for this gene." (PMID 27716847, 2016). "Moreover, there are reports on tumor suppressor activity of other members of the gene families that INPP5K and MYO1C belong to." (PMID 26170120, 2015). "Hic1, Inpp5k, and Myo1c showed reduced expression in tumor samples irrespective of the presence or absence of physical deletion in the candidate region, suggesting the potential involvement of alternative gene silencing regulatory mechanism(s)." (PMID 26170120, 2015). "In light of our previous findings and the known importance of AS events in carcinogenesis and tumour-progression, we checked for cancer-related splice isoforms among our candidate genes for which both transcripts were annotated as protein-coding, such as ANKHD1 in SW480 and MYO1C in SW620." (PMID 31443305, 2019). "Furthermore, as reported in other tumors types, upregulation of DAB2, RND3, TMEM97, CSE1L, MYO1C, and PTPRK have been shown to suppress or functionally redistribute E-cadherin expression in cancer cells, resulting in EMT, increased invasion, advanced tumor stage and poor patient survival." (PMID 27863424, 2016). "There is no earlier report on potential tumor suppressor activity of MYO1C; however, another member of the myosin-I gene family, MYO18B, has been recognized as a tumor suppressor gene candidate in lung, ovarian and colorectal cancer." (PMID 27716847, 2016). "There is no earlier report on the potential tumor suppressor activity of INPP5K and MYO1C, however, overlapping roles in phosphoinositide (PI) 3-kinase/Akt signaling, known to be vital for the cell growth and survival, are reported for both." (PMID 26170120, 2015).
cancer (9 papers, 2014 to 2023). A tumor composed of atypical neoplastic, often pleomorphic cells that invade other tissues. "Myo1b and Myo1c are the best characterized class I myosins involved in cell migration and emergent evidence highlight their role in different types of cancer." (PMID 34974807, 2022). "This is in agreement with a study in human cancer cells, which showed a higher proliferation rate after Myo1C depletion." (PMID 32161327, 2020). "Although roles of MYO1C in the insulin-mediated signaling for glucose receptor transport are well established, details of its potential involvement in cancer development through the PI3K/AKT signaling pathway remain to be investigated." (PMID 27716847, 2016). "This is, to our knowledge, the first report documenting a change of a myosin IC isoform expression in connection to cancer." (PMID 25259793, 2014). "To investigate the potential mechanism/s involved, we performed cell transfections for MYO1C protein over-expression and/or knockdown followed by cell proliferation, cell migration, and cell spreading/adhesion assays to investigate the potential contribution of MYO1C to these cancer phenotypes." (PMID 27716847, 2016).
infection (5 papers, 2016 to 2024). The state of being infected such as from the introduction of a foreign agent such as serum, vaccine, antigenic substance or organism. "The data showed Myo1c‐siRNA infection abrogated liraglutide‐induced Dock5 expression in parallel with cell viability, adhesion, and movement." (PMID 39159301, 2024). "An increase in Myo1c expression was identified upon infection with Aeromonas hydrophila, a Gram-negative bacterium, in Rohu carp (Labeo rohita) liver tissue." (PMID 36672855, 2022).
bacterial diseases (1 paper, 2022). "Unconventional myosin-Ic (Myo1C), known to play an important role in bacterial diseases by encoding a member of the strange myosin family of proteins, was also found in Omy27." (PMID 36672855, 2022).
MYO1C also shares sentences with these, for which no sentence is quoted: Alzheimer disease (1 paper); diabetic nephropathy (1); Insulin resistance (1); leukemia (1); Miller-Dieker syndrome (1); multiple sclerosis (1); Niemann-Pick disease type C (1); ovarian carcinoma (1); pancreatic cancer (1); Parkinson disease 7 (1); rectal tumor (1); rheumatoid arthritis (1); sarcopenia (1); squamous carcinoma (1); type-2 diabetes (1); Usher syndrome (1).